PVALEF (parvalbumin like EF-hand containing)
Synonyms: AATK-AS1
Gene: Protein-coding gene on chromosome 17 (81,165,507 to 81,183,166, forward strand). Ensembl gene ENSG00000225180.
Gene Ontology:
Molecular function: calcium ion binding
Biological process: skeletal muscle contraction
Cellular component: troponin complex
Homologues: Orthologues: chimpanzee PVALEF (96% identical), macaque PVALEF (89% identical), dog PVALEF (75% identical), pig PVALEF (67% identical).